TLR4 (toll like receptor 4)
Diseases named in the same sentence as TLR4 in open-access papers (continued):
Sharing a sentence is not in itself a finding about the gene and the disease.
toxoplasmosis (11 papers, 2013 to 2024). A parasitic disease contracted by the ingestion or fetal transmission of toxoplasma gondii. "What is more, TLR4 had activity in the determination of the T. gondii cyst number of the brain at a chronic phase of toxoplasmosis, observed also at 8 and 12 weeks post-infection." (PMID 23161283, 2013). "Besides the lack of papers on the role of genetic changes within TLR4 in the development of toxoplasmosis, T. gondii infection was reported to trigger TLR4 to activate proinflammatory transcription factors and the expression of the pro-cytokines encoding genes." (PMID 26254559, 2015). "We demonstrate protection of HLA-A*11:01, HLA-A*02:01, and HLA-B*07:02 mice against toxoplasmosis by (i) this novel chimeric polypeptide, containing epitopes that elicit CD8+ T cells, CD4+ T helper cells, and IgG2b antibodies, and (ii) adjuvant activation of innate immune TLR4 and TLR5 pathways." (PMID 33046728, 2020). "Furthermore, these results suggest that activation of TLR4 and TLR5 could be useful for development of vaccines that elicit T cells to prevent toxoplasmosis in humans." (PMID 29263879, 2017).
autoimmune hepatitis (10 papers, 2021 to 2025). Hepatitis caused by autoantibodies. "While TLR3/TLR4-TRIF activation drives the progression of drug-induced liver injury, ischemia-reperfusion liver injury, and autoimmune hepatitis, TRIF exhibits a dual role in ALD and MASLD/MASH." (PMID 38694821, 2024). "One study demonstrated that LDN protects against the inflammatory response induced by autoimmune hepatitis, which may be related to its ability to suppress IL-6 and TNF-α secretion and interfere via modulation of the TLR4/NF-ƙB signalling pathways." (PMID 38720250, 2024). "M2 macrophages were dominant during early stages of immune responses, while TLR4 continued to express highly and expression of TLR2 was decreased, which would resulted in polarization of liver resident macrophages from M2 to M1 to promote the development of chronic autoimmune hepatitis." (PMID 36778150, 2023). "These include Lipid A derivatives (glycolipids) and anti-TLR4 antibody or TLR4 ligand-J KB-122, which has been approved by the Food and Drug Administration (FDA) for the treatment of autoimmune hepatitis (AIH)." (PMID 33671709, 2021).
autoimmune myocarditis (10 papers, 2014 to 2025). Autoimmune myocarditis is an autoimmune disease that affects the heart. "For example, TLR4 activation causes experimental autoimmune myocarditis progress to DCM in mice, which was closely related to PDCM." (PMID 33392258, 2020). "Moreover, induction of phenotypic switching to M1 macrophage polarization via HMGB1-TLR2/TLR4 signaling cascade has been previously associated with age-related cardiac dysfunction and autoimmune myocarditis development." (PMID 35281739, 2022). "TLR4 and downstream-signaling activation showed importance for the induction of autoimmune myocarditis model." (PMID 30046376, 2018). "A model of experimental autoimmune myocarditis (EAM) was established in BALB/c mice on which TLR4 activation by LPS-EB or TLR4 inhibition by LPS-RS was performed to induce chronic inflammation for 5 weeks." (PMID 30046376, 2018). "In the current study, we hypothesize that mitochondrial dynamic balance is disturbed in DCM and involved with TLR4 activation-mediated progression of experimental autoimmune myocarditis (EAM) to DCM." (PMID 30046376, 2018). "confirms that TLRs other than TLR4 are sufficient to activate DCs to induce autoimmune myocarditis." (PMID 24586934, 2014). "We report here that CXCL1/KC production is TLR4 dependent in the context of autoimmune myocarditis." (PMID 24586934, 2014). "(2016) using autoimmune myocarditis model mice, recently demonstrated that HMGB1 facilitated macrophage polarization toward an M1-like phenotype and that this process was dependent on the TLR-4-PI3Kγ-Erk1/2 pathway." (PMID 29847178, 2018).
bacterial pneumonia (10 papers, 2007 to 2025). Acute infection of the lung parenchyma caused by bacteria (e.g., Streptococcus pneumoniae, Haemophilus influenzae, Chlamydia pneumoniae, Mycoplasma pneumoniae, and Legionella pneumophila). "The aspartic acid to glycine substitution at residue 299 polymorphism (896A/G) of the TLR4 was found to be associated with susceptibility to bacterial pneumonia, possibly through impaired first-line defense mechanisms." (PMID 32753695, 2020). "One beneficial function of TLR4/MyD88-triggered MDSCs in the lung is to efferocytose apoptotic neutrophils to help resolve inflammation elicited during bacterial pneumonia." (PMID 24066282, 2013). "The strength of our findings lies in the use of two distinct injury models: LPS, which induces Toll-like receptor 4 (TLR4)-mediated acute inflammation mimicking bacterial pneumonia, and papain, which simulates protease-mediated epithelial injury and allergic-type inflammation." (PMID 41357881, 2025). "TLR4 translocation and an increased TLR4 gene transcription are therefore two likely mechanisms responsible for the elevated TLR4 expression on the surfaces of these cells observed in inflamed lungs or in the lungs of rabbits suffering from Gram-negative pneumonia." (PMID 25071777, 2014). "Indeed, TLR4-deficient mice are more susceptible to gram-negative sepsis due to Salmonella typhimurium and Escherichia coli and to gram-negative pneumonia due to Haemophilus influenzae, Klebsiella pneumoniae, and Acinetobacter baumannii." (PMID 17676990, 2007). "In conclusion, the treatment of bacterial pneumonia by UC-MSCs can be achieved by down-regulating the expression of NLRP3, TLR4 and NF-kB mRNA and protein." (PMID 40271073, 2025). "It is possible that the improved survival mediated by TLR4 inhibition or HPX therapy was due to protection against bacterial pneumonia rather than against storage lesion plus bacterial pneumonia." (PMID 29522519, 2018).
brucellosis (10 papers, 2012 to 2026). Brucellosis is a bacterial infection that spreads from animals to people via unpasteurized dairy products or by exposure to contaminated animal products or infected animals. "Specifically, the association of TLR4 896 A>G and brucellosis remained significant after HWE correction (ORG 2.69; 95% CI 1.67-4.33)." (PMID 24282567, 2013). "Especially, two key factors (CD8+ T cells and TLR4) in human immune profiles could be markedly associated with the progression of brucellosis." (PMID 35659087, 2022). "B. abortus Omp16 lipoprotein would be able to induce a protective immune response via a TLR4-dependent manner and is a promising self-adjuvanting vaccine against brucellosis." (PMID 38533384, 2024). "TLR4 agonists effectively stimulate innate immunity and enhance bacterial clearance in the mouse model of brucellosis." (PMID 38533384, 2024). "The detailed function of TLR4 in the context of a greater number of cell types or tissues in human or animal brucellosis and in larger samples should be further explored in the future." (PMID 35659087, 2022). "Two key factors (CD8+ T cells and TLR4) in human immune profiles may closely correlate with the progression of brucellosis." (PMID 35659087, 2022). "Another study has recently shown that non-synonymous variants (NSVs) of a gene involved in innate immune response (i.e., Toll-like receptor 4, TLR4) are associated with BS; also, the familial Mediterranean fever (MEFV) gene Met694Val mutation seems to confer BS risk in the Turkish population." (PMID 34692721, 2021). "Consequently, transgenic sheep over-expressing TLR4 are an suitable model to investigate the effects of TLR4 on preventing Brucellosis." (PMID 27408716, 2016). "There is some controversy on the role of TLR4 in murine brucellosis." (PMID 22500859, 2012). "Therefore, blocking the binding of S100A8/A9 to TLR4 may inhibit the downstream pro‐inflammatory signal, making it a promising strategy for designing effective therapeutics against acute brucellosis." (PMID 39135683, 2024). "We also found that the expression of TLR-2 (CD282) and TLR-4 (CD284) on all three monocyte subsets, particularly on the CD14++CD16− monocyte subset, increased in brucellosis patients compared with HC." (PMID 28659924, 2017).
cholangiocarcinoma (10 papers, 2020 to 2025). A carcinoma that arises from the intrahepatic biliary tree (intrahepatic cholangiocarcinoma) or from the junction, or adjacent to the junction, of the right and left hepatic ducts (hilar cholangiocarcinoma). "Indeed, activation of TLR4 and high expression of the TLR4 gene are associated with cholangiocarcinoma (CCA) progression and worse disease outcomes, while lower TLR4 levels are associated with tumor growth suppression." (PMID 38191517, 2024). "Li found SNHG1, a long non-coding RNA, acting as a ceRNA (competing endogenous RNA) for miR-140, promotes the expression of TLR4 and activates the NF-ĸB signaling pathway, thus regulating the growth and tumorigenesis of cholangiocarcinoma." (PMID 38577599, 2024). "The small nucleolar RNA host gene 1 (SNHG1)/miR-140/TLR4/NF-κB signaling axis plays a crucial role in cholangiocarcinoma tumorigenesis and progression." (PMID 33083486, 2020). "Given the increasing incidence of cholangiocarcinoma (CCA) worldwide, the role of TLR4 signaling in CCA requires a brief mention." (PMID 37345131, 2023). "Gut-derived LPS engages TLR4 along the hepatobiliary axis to promote cholangiocarcinoma (CCA)." (PMID 41339918, 2025). "S100A8 can activate the Toll-like receptor 4 (TLR4)-NF-κB signaling pathway, which upregulates VEGF expression, and thus, leads to the invasion and metastasis of cholangiocarcinoma cells." (PMID 39895787, 2025). "The outcomes propose a variety of novel targets for intervening in cholangiocarcinoma growth, encompassing gram-negative intestinal bacteria, TLR4, CXCL1, CXCR2, and MDSCs themselves." (PMID 37894256, 2023).
cholestasis (10 papers, 2018 to 2025). Impairment of the bile flow caused by obstruction within the liver, or outside the liver in the bile duct system. "In conclusion, FTA, a key component of forsythia fruit, alleviated liver damage and fibrosis caused by cholestasis via inhibiting the TLR4/NF-κB pathway, extracellular matrix accumulation, and inflammatory cytokine expression." (PMID 37432229, 2023). "Our outcomes revealed that the binding free energy of FTA and receptors was less than −5.0 kcal/mol, indicating that FTA may bind these receptors and regulate TLR4/Myd88/NF-κB signaling, thereby improving liver damage caused by cholestasis." (PMID 37432229, 2023). "Similarly, macrophages have been associated with the pathogenesis of murine parenteral nutrition-associated cholestasis via toll-like receptor 4 (TLR4)-mediated activation and production of interleukin-1 beta (IL-1β)." (PMID 33411796, 2021). "Conversely, cholestasis-induced liver damage in mice is effectively reduced by blocking TLR4 signaling or NF-κB activation." (PMID 31827690, 2019). "Furthermore, the relative mRNA expressions of TLR4 remarkably increased in ANIT-induced cholestasis rats (P < 0.01)." (PMID 34512782, 2021). "Substantial evidence showed that inhibition of the TLR4/MYD88/NF-κB inflammatory pathway played a crucial role in the prevention and treatment of cholestasis." (PMID 37432229, 2023). "Among them, HSP90AA1, TLR4, MMP2, APP, and NFKB1 were the crucial targets of FTA in the treatment of cholestasis." (PMID 37432229, 2023). "Molecular docking data revealed a relatively higher binding ability of FTA with TLR4 and NFKB1, suggesting that FTA was a key component in the treatment of cholestasis by RAIs." (PMID 37432229, 2023). "In addition, murine models of intestinal damage have shown that lipopolysaccharides (LPS) located on the outer membrane of Gram-negative bacteria are associated with Toll-like receptor 4 (TLR-4) activation in Kupffer cells promoting apoptosis, cholestasis, and fibrosis." (PMID 29882922, 2018).
cutaneous leishmaniasis (10 papers, 2012 to 2023). Leishmaniasis affecting the skin. "In contrast, blockage of both TLR2 and TLR4 suppressed the proinflammatory response and parasite load in monocytes/macrophages collected from human cutaneous leishmaniasis caused by Leishmania braziliensis." (PMID 36190414, 2022). "Nonetheless, and similar to TLR2, milder forms of human cutaneous leishmaniasis due to L. braziliensis are associated with higher expression of TLR4." (PMID 31806038, 2019). "Moreover, TLR4 polymorphisms have been associated with susceptibility to cutaneous leishmaniasis in humans." (PMID 31806038, 2019). "In human cutaneous leishmaniasis the up-regulation of TLR2/TLR4 expression in monocytes correlates with disease outcome, their up-regulation expression by macrophages and monocytes is related to healing lesions by increasing ROS and NO production." (PMID 34745100, 2021). "More recently, the formulation of a defined polyprotein anti-Leishmania vaccine candidate in conjunction with TLR4 or TLR9 agonists was evaluated as an immunotherapeutical treatment in a mouse model of cutaneous leishmaniasis." (PMID 22523644, 2012). "TLR4 and TLR2 is expressed in lesions of cutaneous leishmaniasis and TLR2 in blood cells of VL patients, suggesting that these signaling molecules are involved in Leishmania infections." (PMID 26814478, 2016).
head and neck squamous cell carcinoma (10 papers, 2011 to 2025). A squamous cell carcinoma that arises from any of the following anatomic sites: lip and oral cavity, nasal cavity, paranasal sinuses, pharynx, larynx, and salivary glands. "The expression of TLR4 is widely observed in head and neck squamous cell carcinoma (HNSC) and NPC tissues, as well as in several NPC cell lines." (PMID 36497484, 2022). "For instance, loss‐of‐function polymorphisms in TLR4 or P2RX7 have been associated with poorer outcomes in breast and head and neck squamous cell carcinoma (HNSCC) patients receiving anthracycline‐based adjuvant CT." (PMID 40900811, 2025). "TLR-9, TLR-5, TLR-4, TLR-3, TLR-2 and TLR-1 are linked to some clinical parameters of patients afflicted with head and neck squamous cell carcinoma (HNSCC)." (PMID 36224753, 2022). "Finally, TLR3 and TLR4 expression was observed in head and neck squamous cell carcinoma (HNSCC)." (PMID 27191981, 2016). "Moreover, our previous study showed that CD38 deletion upregulates TLR4 expression, and also, there is a paper reporting that CD38 can induce inflammasome-mediated activation of caspase-1 by activating NLRP3 in head and neck squamous cell carcinoma (HNSCC)." (PMID 33860064, 2021).
ileitis (10 papers, 2007 to 2024). "The TLR2 agonists lipoarabinomannan and lipoteichoic acid reduced indomethacin-induced murine ileitis via modulation of TLR4 pathways on macrophages and effects on leukocyte migration." (PMID 29515999, 2018). "In response to TGF-β release, miR-511-5p level is upregulated in monocytes, resulting in their desensitization due to downregulation of TLR4 present on their surface, which controls severe inflammation and dramatically reduce TNFα and other cytokines that are involved in ileitis." (PMID 38743178, 2024). "Given that the immunopathology underlying acute T. gondii induced ileitis is initiated and perpetuated by bacterial LPS via TLR-4-dependent signaling, dampening of TLR-4 dependent signaling reveals an important key stone of mechanism by which PACAP exerts its multi-facetted beneficial effect." (PMID 25238233, 2014). "Gram-negative species such as E. coli and Bacteroides/Prevotella species overgrow the inflamed ileal lumen during ileitis development, and the inflammatory scenario is further perpetuated by TLR-4-dependent signaling of lipopolysaccharide (LPS) derived from intestinal Gram-negative commensals." (PMID 25238233, 2014). "Likewise, we recently reported that oral administration of the TLR4 agonist lipid-A aggravated immunopathology in a murine model of Toxoplasma gondii-induced ileitis, and that genetic deletion of TLR4, or treatment with the LPS scavenger polymyxin-B, ameliorated disease symptoms in this model." (PMID 20161736, 2010). "This is in line with the earlier finding that commensal E. coli accumulated drastically during ileitis in our C57BL/10 mice and displayed a strong pro-inflammatory potential to trigger small intestinal inflammation via TLR4." (PMID 17653282, 2007).
ischemia reperfusion injury (10 papers, 2017 to 2025). Adverse functional, metabolic, or structural changes in ischemic tissues resulting from the restoration of blood flow to the tissue (reperfusion), including swelling; hemorrhage; necrosis; and damage from free radicals. "In an animal model of ischemia-reperfusion injury, it was observed that TLR4 activation was associated with the stimulation of an inflammatory response, which subsequently exacerbated AKI." (PMID 40584714, 2025). "AKI caused by ischemia–reperfusion injury can induce a significant increase in lysine-specific demethylase 1 expression through the AKT pathway, thereby affecting the lysine metabolic pathway and generating oxidative stress and ferroptosis via the TLR4/NOX4 pathway." (PMID 41189893, 2025). "In addition, in hepatic ischemia-reperfusion injury, octreotide and melatonin could reduce the inflammasome-induced pyroptosis by inhibiting the TLR4-NF-κB-NLRP3 pathway." (PMID 35003098, 2021). "Using the rodent models of hepatic ischemia reperfusion injury both in wild type and TLR4 knockout (TLR4 KO) mice, we found that remifentanil preconditioning could inhibit the expression of TLR4 and reduce the inflammatory response induced by HIRI in wild type but not in TLR4 KO mice." (PMID 30765766, 2019). "The aim of this study was to investigate the changes of TLR4/NLRP3 signal during hepatic ischemia-reperfusion injury (HIRI) and to verify whether N-acetyl-L-tryptophan (L-NAT) protected hepatocytes by regulating the activation of TLR4/NLRP3 signal." (PMID 34434653, 2021).
neuropathic pain (10 papers, 2014 to 2025). Chronic pain caused by damage to nerve fibers. "In conclusion, the present study demonstrated that the deficiency of glial TLR4 could decrease mechanical allodynia with synergic TLR4 mediated blockade of impaired spinal autophagy induction in CCI-induced neuropathic pain mice." (PMID 29486776, 2018). "In the neuropathic pain model, mechanical or thermal hyperalgesia was abrogated after inhibition of TLR4." (PMID 37240805, 2023). "Interestingly, acting as TLR4 antagonists, naloxone and naltrexone inhibit the opioid- or LPS-induced TLR4 signaling pathway and reverse TLR4-related neuropathic pain." (PMID 32733481, 2020). "The roles of HMGB1 and TLR4 in neuropathic pain are unknown, and more studies are required to confirm whether the HMGB1-TLR4 interaction is directly involved in the pathogenesis of neuropathic pain." (PMID 25120576, 2014). "Among these glial activation signals, Toll-like receptors (TLRs), particularly Toll-like receptor 4 (TLR4), have been demonstrated as initiators and mediators of neuropathic pain." (PMID 29486776, 2018). "In vivo, EGCG can inhibit the expressions of TLR4, NF-κB, HMGB1, TNF-α, and IL-1β, and promote the expression of IL-10 in neuropathic pain rats." (PMID 24692852, 2014). "Taken together, these findings support the results of this study, reinforcing the proposition that HMGB1 participates in TLR4 spinal activation, triggering the production of inflammatory mediators involved with the nociception during PCT-induced neuropathic pain." (PMID 38384464, 2024). "When TLR4 and RAGE participation in rHMGB1-induced allodynia was evaluated, we verified that the highest effective doses previously reported prevented mechanical allodynia in our PCT-induced neuropathic pain model." (PMID 38384464, 2024). "Consistently, upregulation of TLR4 during the development of DNP in the spinal cord has been identified, and several drugs including coenzyme Q10 and duloxetine contribute to TLR4/Myd88/NF-κB signaling pathway inhibition in the occurrence of neuropathic pain." (PMID 30647535, 2018).